BRCA2 (BRCA2 DNA repair associated)
Diseases named in the same sentence as BRCA2 in open-access papers (continued):
Sharing a sentence is not in itself a finding about the gene and the disease.
breast cancer (continued). "Interestingly, DepMap Cancer Gene Dependency data show that reduced viability (fitness) following PPIA/CYPA-KO is more commonly seen in breast cancer cell lines with reduced BRCA2 copy number." (PMID 38943005, 2024). "In this cohort of young breast cancer patients, 14 % were BRCA1 or BRCA2 P/LP variant carriers, which stands in accordance with other reports, including one published by the group, showing a 16.5 % BRCA mutation prevalence among 79 luminal breast cancer young patients (below 36 years)." (PMID 39208653, 2024). "In the patients with HER2-low breast cancer, patients with homologous recombination related genes (HRRGs) defects had an HRD score about twice that of those without related genes mutations, and were at higher risk of acquiring ARID1A, ATM, and BRCA2 mutations." (PMID 38366907, 2024). "As the BRCA1 familial variant was not sufficient to explain both pancreatic cancers, those in the patient and his sister, as well as their mother’s breast cancer, we re-initiated a CPG analysis and this showed that he carried two pathogenic variants: the known familial BRCA1 PV, and a BRCA2 PV." (PMID 38929805, 2024). "Additionally, mammography detected 33% of breast cancers in BRCA1 mutation carriers and 43% in BRCA2 mutation carriers." (PMID 38791944, 2024). "By contrast the risk for breast cancer for BRCA1/2 mutation carriers by 70–80 years of age is roughly five to seven times higher (55%–72% of women who inherit a harmful BRCA1 variant and 45%–69% of women who inherit a harmful BRCA2 variant)." (PMID 38717180, 2024). "For individuals carrying BRCA1 or BRCA2 mutations and diagnosed with HER2- breast cancer, treatment with PARP inhibitors such as olaparib and talazoparib may be considered." (PMID 38167124, 2024). "For Korean breast cancer patients, the prevalence of BRCA1/2 mutation for patients with a family history of breast or ovarian cancer is 22.3%, and the cumulative risk of breast cancer is 72.1% for BRCA1 and 66.3% for BRCA2 mutation carriers." (PMID 38254240, 2024). "Moreover, the cumulative risks of developing breast cancer in male BRCA1 and BRCA2 mutation carriers are 1% and 7–8%, respectively, significantly higher than the 0.1% risk observed in the average male population." (PMID 39590130, 2024). "This may be possibly due to the well-known gene- and gender-specific role of BRCA1/2 PVs in the two sexes, with BRCA1 PVs mainly involved in females, while BRCA2 PVs are mainly involved in male breast cancers." (PMID 38339299, 2024). "The first breast cancer gene (BRCA1) was identified in 1994, showing close correlation with breast cancer development when becoming mutated, while the second breast cancer gene (BRCA2) was announced in 1995." (PMID 38672654, 2024). "The control group consisted of 62 age-matched women with no prior history of cancer, selected for high-risk breast cancer surveillance due to BRCA1 or BRCA2 mutations." (PMID 39682278, 2024). "Although recent cohort studies suggest a possible survival benefit for prophylactic mastectomy in unaffected BRCA1 carriers, there are no data to suggest a survival benefit relative to MRI surveillance in unaffected BRCA2/PALB2 carriers or carriers with a prior history of breast cancer." (PMID 38248108, 2024). "Ashok Venkitaraman has made seminal discoveries elucidating the tumour suppressive mechanisms that maintain genome integrity through his pivotal studies on the breast cancer gene BRCA2, thereby illuminating the role of a class of genes often inactivated in human cancers." (PMID 39711301, 2024). "Nonetheless, a study of the remaining lifetime risk for the subset of women who were older than 65 years in the population-based CARRIERS project indicated that BRCA1, BRCA2, and PALB2 PVs were associated with enough breast cancer risk to warrant high-risk screening." (PMID 37861889, 2024).
breast cancer (continued). "Additionally, 202 patients had previously been diagnosed with breast cancer, with 141 being carriers of the BRCA1 mutation and 61 carrying the BRCA2 mutation." (PMID 39594243, 2024). "It calculates breast cancer risk by considering factors such as age, family history of breast cancer, hormonal factors (e.g., age at menarche and age at first birth), breast density, and the presence of specific genetic mutations (e.g., BRCA1 and BRCA2)." (PMID 38674216, 2024). "PVs in BRCA1, BRCA2, CHEK2, and ATM increase the lifetime cancer risk of breast cancer." (PMID 38929805, 2024). "Third, due to the small number of breast cancer patients carrying BRCA gene variants, this study was unable to analyze the differences in clinical characteristics between patients carrying BRCA1 gene variants and those carrying BRCA2 gene variants." (PMID 38167124, 2024). "Upregulated expression of BRCA1 and BRCA2 genes was reported in BC and ovarian cancer, furthermore, high BRCA1 gene expression was demonstrated to increase the risk of early distant metastasis in ER + breast cancer patients." (PMID 38165507, 2024). "However, other studies reported higher cumulative breast cancer risk (72%) to age 80 for BRCA1 and 69% for BRCA2 carriers." (PMID 37781190, 2023). "Pathologic and ultrasound features of BRCA1 and BRCA2 breast cancers were previously assessed, although several essential variables, such as vascularity or elasticity, remain unknown." (PMID 36905492, 2023). "For example, advanced breast cancer patients with a germline BRCA1 or BRCA2 PV have a greater benefit to PARP inhibition than individuals with a somatic BRCA1 or BRCA2 PV, and the FDA-approval for PARP inhibition is currently confined to those with a germline PV4." (PMID 37833309, 2023). "In this review, we discuss surgical treatment options for patients with breast cancer known to have a high-penetrant cancer-predisposing gene, like the BRCA1 and BRCA2, and address the oncological safety of less aggressive surgical options, for both patients and unaffected carriers." (PMID 37781190, 2023). "Moreover, the risks of esophageal cancer and lymphoma were markedly elevated in male relatives of BRCA1 carriers, and the risks of esophageal, kidney, and breast cancers in male relatives of BRCA2 carriers were also increased." (PMID 36861435, 2023). "Breast-cancer genes 1 and 2 (BRCA 1, BRCA2) encode for proteins involved in tumor suppression." (PMID 36614207, 2023). "Two studies were conducted using familial breast cancer cases with no BRCA1 or BRCA2 pathogenic variants and controls from the general population." (PMID 36707629, 2023). "The most significant genes implicated in hereditary breast cancer are the BRCA1 and BRCA2 genes, and pathogenic mutations in these genes together accounting for about 30% of high-risk breast cancer families and explain about 15% of the breast cancer familial relative risk." (PMID 38020349, 2023). "Additionally, genetic factors also played a key role in the growing incidence of breast cancer in the SACU region, and it’s confirmed the variants in the two major genes, BRCA1 and BRCA2, and in five other genes in the patients in South Africa." (PMID 36761973, 2023). "However, it was associated with increased survival following breast cancer when considering BRCA1 and BRCA2 carriers together and BRCA1 carriers alone." (PMID 36900415, 2023).
breast cancer (continued). "However, their mutations are associated with cancer, especially breast cancer, and the cancer risk varies with the mutation position in BRCA1 or BRCA2 genes." (PMID 36765522, 2023). "Among breast cancer patients the most prevalent occur in BRCA2, CHEK2, BRCA1 and ATM." (PMID 37790698, 2023). "BRCA2 was identified in families with a high incidence of breast cancer." (PMID 36976771, 2023). "Recently published studies assessing the clinical validity of genes frequently tested in hereditary breast and ovarian cancer mostly agree that ATM, BRCA1, BRCA2, CHEK2, and PALB2 are strongly associated with a risk of breast cancer (overall with a p value of less than 0.0001)." (PMID 37239898, 2023). "Furthermore, a more advanced stage at diagnosis and the presence of multiple foci of breast cancers are more common in patients with BRCA1 and BRCA2 mutations than in patients with sporadic tumors." (PMID 35778884, 2023). "However, breast cancer can occur in younger females due to certain risk factors, such as the inheritance of mutated BRCA1 or BRCA2 genes or the use of contraceptives." (PMID 38143654, 2023). "Consistent with our finding in PDAC, a publicly available database for Genomics of Drug Sensitivity in Cancer revealed that PARP inhibitors and BET inhibitors (e.g., JQ1, PFI-1, I-BET-762) are preferentially cytotoxic in mutant BRCA2 context in breast cancer and pan-cancer, respectively." (PMID 37735513, 2023). "Typically, these criteria were based on early studies of BRCA1 and BRCA2 and are based on age at breast cancer diagnosis, ethnicity (e.g., Jewish), clinical characteristics of breast cancer (e.g., bilateral breast cancer, triple‐negative breast cancer), and family history of cancer." (PMID 36544278, 2023). "In support of this hypothesis, our team recently reported the breast cancer risk modifying effect of an ALDH2 common polymorphism, rs10744777, among Polish carriers of the BRCA2 p.K3326* mutation." (PMID 37943872, 2023). "The carrier of the BRCA2/PTEN mutation presented an epithelial thyroid cancer and a breast cancer." (PMID 37444530, 2023). "Even if the relative risks for anthropometric measures and breast cancer in BRCA1 and BRCA2 variant carriers are similar to those found in the general population, the absolute excess risks will be higher for BRCA1 and BRCA2 variant carriers because of the higher background breast cancer risk." (PMID 37340476, 2023). "Hereditary breast cancer is most commonly attributed to germline BRCA1 and BRCA2 gene variants." (PMID 37895014, 2023). "Whole-exome sequencing data from 98 BRCA1/BRCA2/PALB2 founder mutation-negative Northern Finnish breast cancer cases with indications of hereditary disease susceptibility was used for the identification of rare CNVs." (PMID 37578974, 2023). "While among those with CC/CT genotypes of the ALDH2 rs10744777, the carriers of the BRCA2 p.K3326* mutation did not have a higher risk of breast cancer compared to non-carriers (OR = 1.05, 95% CI: 0.73–1.51, P = 0.81)." (PMID 37943872, 2023). "The question remains open as to whether our findings are restricted to BRCA1 and BRCA2 or if they represent a small part of a global reduction of circRNAs in breast cancer." (PMID 37046838, 2023). "In addition, 20 of the 69 patients who had a prior history of breast cancer had a relapse, leading to death in two patients (BRCA1- and BRCA2-mutated)." (PMID 36831483, 2023). "Since brain metastases occur in approximately half the patients with advanced breast cancer with BRCA mutations, and BRCA2 mutation prevalence reached 22% in our meta-analysis, PARP inhibitors could be promising tools for the treatment of brain metastases." (PMID 36980614, 2023).
breast cancer (continued). "We hypothesized that due to their histological differences, BRCA1 and BRCA2 breast cancers demonstrate different imaging characteristics on ultrasound." (PMID 36905492, 2023). "Breast cancer patients were not different from BRCA1- (p = 0.405) or BRCA2- (p = 0.191) mutated patients." (PMID 37623237, 2023). "We assessed the PREDICT v 2.2 for prognosis of breast cancer patients with pathogenic germline BRCA1 and BRCA2 variants, using follow-up data from 5453 BRCA1/2 carriers from the Consortium of Investigators of Modifiers of BRCA1/2 (CIMBA) and the Breast Cancer Association Consortium (BCAC)." (PMID 37173335, 2023). "For example, screening for the BRCA-1 and BRCA-2 genes in breast cancer could have important implications for the early warning of breast cancer." (PMID 37181711, 2023). "Among these genes, Breast Cancer 1 (BRCA1) and Breast Cancer 2 (BRCA2) have been reported to have variations that increase the risk of developing breast and ovarian cancers by more than 60% basically suggesting these variations as one of the leading causes of breast and ovarian cancers." (PMID 36896237, 2023). "PARP inhibitors inactivate the PARP family of enzymes and are approved for use in the treatment of metastatic germline BRCA1 or BRCA2-mutated breast cancers and in the adjuvant setting for high-risk, HER2-negative germline BRCA1 or BRCA2-mutated early breast cancer." (PMID 37173991, 2023). "Finally, we considered the two studies published so far testing the association between FANCM MVs and breast cancer risk conducted using familial designs and excluding carriers of BRCA1 or BRCA2 pathogenic variants." (PMID 36707629, 2023). "Breast cancer 2, early onset (BRCA2) is a tumor suppressor gene first identified in humans." (PMID 36851449, 2023). "As a consequence, considering the important roles of BRCA1 and BRCA2 mutations in development of breast cancer, strategies in supplying the wild type BRCA1 and BRCA2 gene could be promising as a therapeutic option." (PMID 36631481, 2023). "Moreover, we did not perform germline sequencing for variants that predispose to breast cancer, like BRCA1 and BRCA2 pathogenic variants." (PMID 37599285, 2023). "In early breast cancer, OlympiA was a large phase 3 randomised clinical trial testing effectivity of olaparib in patients with gBRCA1 and BRCA2 PVs HER2 negative high-risk breast cancer." (PMID 38414963, 2023). "Moreover, the incidence rate of BRCA2-mutant breast cancer peaked in the population year from 40 to 49 forecast from the study." (PMID 37476378, 2023). "In conclusion, our study reported a cohort of Taiwanese breast cancers harboring mutations in BRCA1, BRCA2, and PALB2 through tumor-only sequencing, which underscores the impact of BRCA1/2 and PALB2 on breast cancer risk and potential therapeutic opportunities." (PMID 38098088, 2023). "Molecular tests such as phosphoinositide 3-kinase mutations, breast cancer susceptibility gene 1 or 2 mutations (BRCA1 OR BRCA2) and PD-L1 expression were not done and the relevant targeted therapy was not given." (PMID 37396100, 2023).
breast cancer (continued). "Overall, we developed an innovative method to study linear splicing and backsplicing, described the repertoire of BRCA1 and BRCA2 circRNAs, including 15 novel ones, and showed for the first time that a disequilibrium between BRCA1 and BRCA2 circRNAs and mRNAs plays a role in breast cancer." (PMID 37046838, 2023). "Previously, we have identified pathogenic mutations of BRCA1, BRCA2, CHEK2, and PALB2 in about half of 1018 Polish families with hereditary breast cancer, and we have observed that 18 founder mutations are responsible for about 80% of all the mutations detected in these genes." (PMID 37510234, 2023). "BRCA2 expression is lower in canine mammary tumors than in unaffected mammary tissues and therefore could be another possible mechanism leading to tumorigenesis." (PMID 37835752, 2023). "We found that higher young-adult BMI is associated with lower premenopausal breast cancer risk in both BRCA1 and BRCA2 variant carriers in the retrospective analysis, with consistent, although not statistically significant, risk estimates in the prospective analysis." (PMID 37340476, 2023). "A similar pattern (with an association for BRCA1- but not BRCA2-associated breast cancer) has been observed for oral contraceptive use." (PMID 37340476, 2023). "Moreover, breast cancer in young patients was strongly associated with family history and genetic mutations in the BRCA1 or BRCA2 genes leading to the development of breast and ovarian cancers." (PMID 37143985, 2023). "For breast cancer patients, the results of the TBCRC-048 and TBB trials suggested further exploration of PARP inhibitors in metastatic or advanced breast cancers with HR-associated mutations beyond BRCA1 and BRCA2." (PMID 38098088, 2023). "Therefore, identifying genes associated with breast cancer susceptibility, such as BRCA1 and BRCA2, is important for improving surveillance and developing effective preventive interventions." (PMID 37138170, 2023). "The annual diagnosis of new breast cancer cases stands at 6000 cases in Kenya, which could hypothetically imply that the extent of BRCA1 and BRCA2 mutation is higher in our population and goes undetected due to lack of screening." (PMID 37719058, 2023). "A large sequencing study on female breast cancer found that BRCA1 and BRCA2 mutations could account for 2% of the cases (subtracting the proportions in healthy individuals) and that all germline mutations accounted for 5.6% of the cases." (PMID 36882784, 2023). "Only in one instance did a breast cancer patient have both BRCA1 and BRCA2 variants." (PMID 37306523, 2023). "Here, we demonstrate, for the first time, that SOC therapies used in ER+ breast cancer induce DNA damage, and toxic PARP1 trapping upon generation of a functional BRCAness phenotype through loss of key DNA repair proteins, including BRCA1, BRCA2 and RAD51." (PMID 37914699, 2023). "Patients who could have a higher hereditary risk of developing breast cancer or who might benefit from particular treatments or preventive measures might be identified by genetic testing, such as finding BRCA1 and BRCA2 mutations." (PMID 38192969, 2023). "A 34‐year‐old woman with breast cancer and BRCA2: p.Gln3047Ter was treated with olaparib." (PMID 37361653, 2023). "Exploratory analyses of high-dose alkylating chemotherapy trials have suggested that BRCA1 or BRCA2-pathway altered (BRCA-altered) breast cancer might be particularly sensitive to this type of treatment." (PMID 37689749, 2023). "Thus, considering our in vitro and in vivo findings, BRCA1- and BRCA2-based gene therapy using CA NPs as delivery vector reveals a highly promising approach to treating breast cancer." (PMID 36631481, 2023).